TNF (tumor necrosis factor)
Diseases named in the same sentence as TNF in open-access papers (continued):
Sharing a sentence is not in itself a finding about the gene and the disease.
psychosis (continued). "The authors suggested that IL-1β, IL-2, and IL-6 could serve as markers for psychosis, while TNF-α, IL-17, and IFN-γ were still elevated after antipsychotic treatment." (PMID 30766494, 2018). "Our results indicate increased inflammation and potential apoptotic-related activation in the midbrains of inflamed patients with psychosis through increased TNFSF receptor synthesis and suggest that glial cells are poised to respond to increased TNF directly." (PMID 41567988, 2026). "A psychosis signature (ρ = 0.27; P = .002) differentiated ROP from CHR-P with elevated IL-6, TNF-α, and reduced CRP, alongside GMV shifts in corticothalamic circuits." (PMID 41405910, 2025). "Our finding of decreased TNF-α and some complement factors in CHR populations is in contrast to studies reporting increased immuno-inflammatory levels in patients with established psychosis." (PMID 36631451, 2023). "In first-episode psychosis, interferon-γ (IFN-γ), IL-1RA, IL-1β, IL-6, IL-8, IL-10, IL-12, sIL-2R, TGF-β, and TNF were all significantly increased, and levels of IL-4 were significantly decreased." (PMID 32256401, 2020). "Mean levels of IL6 (g = 0.62), TNFα (g = 0.56), interferon-γ (IFNγ) (g = 0.32), transforming growth factor-β (g = 0.53), and interleukin-17 (IL17) (g = 0.48) were elevated in psychosis." (PMID 30407606, 2019). "Antipsychotic-naïve patients with first-episode psychosis show elevated IL6, TNFα, IFNγ, IL17, and TGFβ levels compared with healthy controls." (PMID 30407606, 2019). "Epidemiological studies have shown that elevations in maternal C-reactive protein (CRP) and pro-inflammatory markers, such as cytokines IL-8 and TNFα, in addition to elevations in IL6 in childhood, predict psychotic disorder." (PMID 27650124, 2016). "To date, only few studies have investigated cytokine levels in subjects with first-episode psychosis, reporting higher serum or plasma levels of IL-1β, IL-6, IL-12, INF-γ, TNF- α, TGF- β and soluble IL-2 receptor." (PMID 22749891, 2013). "Risperidone treatment significantly lowered levels of IL-6 and TNF-α in patients with chronic disease, while this effect was not evident in individuals experiencing their first episode of psychosis." (PMID 40153412, 2025). "Although IL-6 and TNF-α have been already previously suggested as a possible important target for patients with treatment-resistant psychosis and with prevalent negative syndrome, the findings of increased IL-10 were more unexpected." (PMID 33667853, 2021). "Gene expression analyses conducted only in those cytokines that were different in the serum (IL-1α, IL-1β, IL-6, IL-8 and TNF-α) revealed significantly increased mRNA levels of IL-1α (d = 0.6), IL-6 (d = 0.7) and TNF-α (d = 1.6) in first-episode psychosis patients when compared with controls." (PMID 22749891, 2013). "An updated review in 2019 reported increasing levels of IL-6, TNF-α, and IL-1β in different groups of patients, including first-time psychosis without medication and patients with first-time psychosis who were often treated with antipsychotics and chronic patients and patients with acute recurrence." (PMID 37644489, 2023). "The finding of significantly higher levels of TNF-α in agitated patients when compared to non-agitated patients was also replicated in a subgroup analysis where the psychosis group was excluded (22.84 ± 18.23 vs 15.31 ± 19.22, Mann-Whitney U = 4841.0, d = 0.13, p = 0.025)." (PMID 31509578, 2019). "Our meta-analysis found that neutrophil/lymphocyte ratio, TNF, CRP, IL-6, and total WBC were elevated in youth with threshold psychosis compared to youth without threshold psychosis, extending results from adult populations." (PMID 38141839, 2024). "Youth with TPD had higher TNF (Hedge’s g = 0.38, 95%CI0.06 – 0.69, k = 4, N = 247, I2 = 34.6%) compared to youth without psychosis in the meta-analysis." (PMID 38141839, 2024).
psychosis (continued). "As hypothesized, meta-analyses found elevations of biomarkers often considered “proinflammatory,” specifically neutrophil/lymphocyte ratio, TNF, CRP, IL-6, and total WBC, in youth with threshold psychosis compared to youth without psychosis." (PMID 38141839, 2024).
pulpitis (46 papers, 2007 to 2026). Inflammation of the dental pulp. "The proinflammatory cytokines mentioned to be useful as a diagnostic tool in pulpitis and acute inflammation were IL-1 β, TNF-α, IL-6, and IL-8." (PMID 38893626, 2024). "Lipopolysaccharide (LPS) is a potent stimulator of pulpitis that has been found in inflamed pulp tissue, causing the release of inflammatory cytokines including TNF-α, IL-1β, and IL-6." (PMID 36788505, 2023). "Inflammatory factors associated with pulpitis and apical periodontitis in immature permanent teeth, such as IL, TNF, and IFN, modulate the host immune response, forming a complex regulatory network that affects the development of the immature permanent teeth by activating or inhibiting MSCs." (PMID 40922724, 2025). "Additionally, in mouse models of pulpitis and apical periodontitis, the dolognawmeter has been used to show that overexpression of tumor necrosis factor-alpha (TNFα) causes functional allodynia and pain-induced gnawing dysfunction." (PMID 36979200, 2023). "A previous study showed that SOX9, as a downstream target of TNF-α, plays an important role in dental pulp inflammation and immune responses." (PMID 41207115, 2026). "Both IL-1β and TNFα are typical proinflammatory cytokines participating in the pathological process of pulpitis." (PMID 40414936, 2025). "In conditions like irreversible pulpitis, IL-1β and TNF-α are markedly upregulated in necrotic pulp tissue, contributing to local inflammatory activation." (PMID 41142308, 2025). "Its expression increases progressively during irreversible pulpitis and correlates significantly with pro-inflammatory cytokines (interleukin-1beta (IL-1β), IL-6, tumor necrosis factor-alpha (TNF-α))." (PMID 40708698, 2025). "This study confirmed that the expression of TLR4 on the cell bodies of TG neurons significantly increased after pulpitis, which was accompanied by increased TNF-α expression and CGRP immunofluorescence intensity in the TG." (PMID 40531313, 2024). "The number of TNF-α-positive cells in the pulpitis significantly increased at 24 h after pulpitis induction, reaching a peak at 72 h and lasting for four weeks." (PMID 40531313, 2024). "Immunohistochemistry staining results showed that at two weeks after pulpitis induction, the pulp had many TNF-α-positive cells." (PMID 40531313, 2024). "In particular, macrophages play critical role in the onset of pulpitis by producing tumor necrosis factor-α (TNF-α)." (PMID 38304347, 2024). "IL-1β, TNF-α, and IL-6 are inflammatory mediators that have been widely reported to involve the inflammatory process and potentiate pain in pulpitis." (PMID 38627713, 2024). "Specifically at 72 h after pulpitis induction, the periapical exudate area showed a significant presence of TNF-α positive cells, whereas TNF-α expression noticeably decreased in the Cur group." (PMID 40531313, 2024). "An essential inflammatory mediator in pulpitis, TNF-α stimulates the NF-κB signaling pathway to mediate the inflammatory process of pulp tissue." (PMID 37179325, 2023). "The GSE77459 dataset screened 166 IR-DEGs and was enriched for three signal pathways involved in pulpitis development: chemokine signaling, TNF signaling, and NF-κB signaling." (PMID 37179325, 2023). "Accumulating studies have proven the contribution of the inflammatory response to irreversible pulpitis, including the significant upregulation of cytokines such as IL-8, TNF-α, and RAGE." (PMID 37208635, 2023). "In this regard, the results of a reversible pulpitis model showed that IL-1β, IL- 6, and TNF-α gene expressions were elevated in LPS-exposed inflamed pulp tissues." (PMID 36788505, 2023). "Pulpitis often occurs alongside inflammation, so we focused on differential expressed circRNAs related signaling pathways, including TNF, NF-κB, NLRP3 inflammasome, MAPK, and Wnt signaling pathways." (PMID 35786385, 2022).
pulpitis (continued). "Pezelj-Ribaric reported that expression of TNF-α differs between symptomatic and asymptomatic irreversible pulpitis and can be a potential biomarker for determining severity of pulpitis." (PMID 36463168, 2022). "Pulpitis is characterized by the production of high levels of pro-inflammatory cytokines including TNFα, IL-4, IL-6, IL-8, IL-10 and CXCL8." (PMID 35902880, 2022). "In clinical research, the amount of TNF-α in dental pulp tissue of pulpitis was much higher than that in normal pulp tissue." (PMID 34154572, 2021). "Studies have shown that inflammatory factors such as TNF-α, IL-6 and IL-8 are closely related to the development of pulpitis." (PMID 34154572, 2021). "Immunohistochemistry staining was used to detect changes of the expression of EZH2 and tumor necrosis factor alpha (TNF-α) in dental pulp inflammation." (PMID 34899918, 2021). "Although current studies have indicated the relationships between pulpitis and cell factors like interleukin, TNF-α, and NK-κB, the related studies on the effect of CFs on pulpitis are relatively less." (PMID 34630628, 2021). "To figure out the epigenetic regulation of autophagy during pulpitis, we screened several groups of histone methyltransferases and demethylases in response to TNFα treatment." (PMID 34434926, 2021). "Taking the tumor necrosis factor-α (TNF-α) as an example, it has been shown that TNF-α is a pleiotropic cytokine that is upregulated in pulpal tissues of teeth with irreversible pulpitis." (PMID 33777260, 2021). "For example, let-7c attenuated the severity of pulpitis by inhibiting the NF-κB pathway in inflammatory disorders as NF-κB pathway increased the production of the inflammatory cytokines IL-1β and TNF-α and decreased stem cell viability." (PMID 32960786, 2020). "Furthermore, Remodelin significantly lowered TNF-α and IL-1β protein levels in the dental pulp of rats with pulpitis, concurrently reducing inflammatory cell infiltration within the dental pulp tissue." (PMID 40362562, 2025). "The experimental results of this study found that TNF-α was highly expressed on MCs induced by pulpitis, and the application of Cur could significantly reduce the expression of TNF-α." (PMID 40531313, 2024). "Using TNF- α only cannot fully reproduce the pulpitis microenvironment." (PMID 38540786, 2024). "In our ex vivo pulpitis model, not only primary dental pulp (DP) cells but also immortalized dental pulp (DP-1) cells exerted the prominent ability to induce TNF-α production in macrophages, which suggested that dental pulp cells secrete essential inducer molecules for pulpitis." (PMID 38304347, 2024). "Based on the possible mechanism that luteolin antagonizes the interaction between PKR and PACT to inhibit PKR activation, which is critical for MV-induced TNF-α induction in macrophages and subsequent onset of pulpitis, we validated the therapeutic effect of luteolin on pulpal inflammation." (PMID 38304347, 2024). "Gene expression profiles and bioinformatics analysis confirmed that M0 macrophages and neutrophils play an irreplaceable role in pulpitis immunity, and the critical genes in the immune reaction to pulpitis are suggested to be IL-6, TNF-α, IL-1β, CXCL8, and CCL2." (PMID 37179325, 2023). "On the other hand, there is a more increased release of active MMPs in pulpitis than in healthy pulp tissue, indicating their role in pulp inflammation: released cytokines (IL-1β) and tumor necrosis factor-α (TNF-α) in pulp inflammation, activate MMP-1, MMP-2 and TIMP1 gene expression." (PMID 36012195, 2022). "In the pulpitis, LPS, TNFα and IL-6 are released at high levels." (PMID 35902880, 2022). "Both trauma and infection, which result in pulpitis, can lead to an inflammatory microenvironment characterized by the accumulation of inflammatory cells, which release proinflammatory cytokines, including tumour necrosis factor-α (TNF-α)." (PMID 34154572, 2021). "The expression of TNF-α gradually increased in dental pulp inflammation." (PMID 34899918, 2021).
pulpitis (continued). "Taken together, Panx3 was firstly proved to be a negative regulator of TNF‐α‐mediated inflammatory response and may be a therapeutic target of dental pulp inflammation." (PMID 27679980, 2017). "During pulpitis, human dental pulp tissues express high levels of TNF-α and IFN-γ." (PMID 28098169, 2017). "Hence, TNF‐α probably contributes to the progression of dental pulp inflammation via activating both extracellular and intracellular pathways of protein degradation in the dental pulp tissue." (PMID 27679980, 2017). "Human dental pulp tissue with irreversible pulpitis expresses high levels of TNF-α and IFN-γ4." (PMID 26775677, 2016). "The highestconcentrations of TNF-α, with regard to clinical classification, were found insymptomatic reversible pulpitis, and the difference was statisticallysignificant in comparison with irreversible asymptomatic pulpitis and healthypulp." (PMID 18320014, 2007). "Thus, targeting necroptosis by inhibiting DAMPs like HMGB1 and pro-inflammatory cytokines such as TNF-α may reduce inflammatory mediators, disrupt the inflammatory cycle, and promote pulp tissue repair, offering a promising therapeutic strategy for pulpitis." (PMID 41142308, 2025). "TNF-α binds to its receptors on immune cells and endothelial cells, initiating a cascade of inflammation such as cytokine production, leukocyte recruitment, and endothelial activation, leading to detrimental effects, including tissue damage and inflammation such as pulpitis." (PMID 39253601, 2024). "We also found decreased expression of TNF-α within enlarged MCs, which suggested that Cur reduced allergic inflammatory reactions by inhibiting the degranulation of MCs in the TG, reducing neuronal excitability and weakening the neuroimmune response and pain sensitivity induced by pulpitis." (PMID 40531313, 2024). "In addition, TNFα and IL-6 are also highly expressed in the pulpitis." (PMID 35902880, 2022). "At six weeks after pulpitis induction, many TNF-α positive cells still occurred in the periapical granulation tissue, whereas the Cur group showed a significant reduction in TNF-α expression." (PMID 40531313, 2024). "Our results demonstrated IL-6, TNF-α TNF, IL-1β, CXCL8 and CCL2 are closely related to the immune infiltrating cells in pulpitis." (PMID 37179325, 2023). "It has been reported that HIF-1α promotes the expression of IL-1β and TNF-α in inflammatory dental pulp cells, and HIF-1α is involved in the development of dental pulpitis from reversible to irreversible pulpitis." (PMID 36385758, 2022). "TNFα is an inflammatory cytokine and TNFα stimulation of HDPCS is often used as an effort to replicate the cell status of pulpitis in vitro." (PMID 34434926, 2021). "We therefore analyzed the expression levels of a Th1 cytokine (TNF-α) and a Th2 cytokine (IL-6) in the MMP-3 treated pulpitis tissues." (PMID 23285075, 2012). "Some generated a transgenic mouse model which conditionally overexpressed TNF-α, and bred these mice with a dentin matrix protein 1 (DMP1)-Cre line for overexpression of TNF-α solely in the tooth pulp and bone, forming pulp inflammation resembling pulpitis." (PMID 40351786, 2025). "After administering Cur by intraperitoneal injection, the expression levels of Toll-like receptor 4 (TLR4), CGRP, glial fibrillary acidic protein (GFAP), fractalkine (CX3CL1), Tumor necrosis factor (TNF-α), and other factors were examined in the TG of pulpitis-induced rats." (PMID 40531313, 2024). "IL-6, TNF-α, IL-1, CXCL8, and CCL2 may be essential molecule of the immune response regulation network in pulpitis." (PMID 37179325, 2023). "DEGs involved in pulpitis were significantly enriched in seven signaling pathways (i.e., NOD-like receptor (NLR), Toll-like receptor (TLR), NF-kappa B, tumor necrosis factor (TNF), cell adhesion molecules (CAMs), chemokine, and cytokine-cytokine receptor interaction pathways)." (PMID 33777260, 2021).
pulpitis (continued). "In dental pulp inflammation, HDPCs express chemokines including CCL2, which could be induced by LPS or TNF-α stimulation." (PMID 34899918, 2021). "Therefore, IL-6, TNF-α, IL-1β, CXCL8, and CCL2 may participate in the occurrence and development of pulpitis by regulating the corresponding immune cells, which needs further experimental verification." (PMID 37179325, 2023). "Dental pulps with pulpitis suffer higher expressions of proinflammatory cytokines (IL-1α, IL-1β, IL-6, and TNF-α) and innate immune response (TLR2, TLR4) than pulps without pulpitis." (PMID 31695620, 2019). "The pulp tissues in the severe pulpitis model at 3 days after MMP-3 or saline-treated were already necrotic; we could not detect either IL-6 or TNF-α protein (data not shown)." (PMID 23285075, 2012).